PROS1 (protein S)
Diseases named in the same sentence as PROS1 in open-access papers (continued):
Sharing a sentence is not in itself a finding about the gene and the disease.
thrombosis (continued). "The importance of protein S as a cofactor in the anticoagulant protein C system is illustrated by the increased risk of venous thrombosis in individuals with a hereditary deficiency of the protein." (PMID 18957140, 2008). "Similar findings were noted in a series of 277 Dutch patients with deep vein thrombosis: 8.3 percent had an isolated deficiency of antithrombin, protein C, protein S, or plasminogen compared to 2.2 percent of controls." (PMID 16968541, 2006). "The odds ratio for thrombosis in affected subjects was 11.5, and the study showed that measurement of free protein S antigen levels was predictive of the mutation and deficiency." (PMID 16968541, 2006). "Protein S deficiencies are associated with superficial and deep vein thrombosis and pulmonary embolism." (PMID 16827935, 2006). "In our patient, therapy with oral anticoagulant was initiated because of the known risk of the recurrence of thrombosis in cases of protein S deficiency." (PMID 15448814, 2004). "Blood samples with decreased protein S-specific activity may increase the risk of developing thrombosis, even if the activity and antigen levels are normal." (PMID 41567132, 2026). "Participants also had lower levels of natural anticoagulants like antithrombin, protein C, and protein S. These changes suggest a higher risk for thrombosis that increases with higher doses of E2 and blood levels of E2, especially in women who are in late postmenopause." (PMID 41048432, 2025). "Protein S deficiency, whether inherited or acquired, remains a significant risk factor for thrombotic events, predominantly venous thrombosis." (PMID 40084314, 2025). "There is preferential venous thrombosis over arterial thrombosis in protein S-deficient patients." (PMID 40084314, 2025). "Venous thrombosis may occur in a similar mechanism to arterial thrombosis but acquired protein S deficiency can also be a cause." (PMID 40018474, 2025). "The strong association between genetic or acquired protein C and protein S deficiencies and increased risk of venous thrombosis suggests that protein C and protein S play important and central roles in controlling the initiation and propagation stages of the coagulation cascade." (PMID 40041162, 2025). "However, it was not clear that the anti-phospholipid antibody-seropositive patients exhibited a propensity for thrombosis in the presence of acquired protein S deficiency." (PMID 39533629, 2024). "The presence of anti-cardiolipin IgG antibodies originally poses a risk of arteriovenous thrombosis, but this combined with a decrease in protein S activity appears to have resulted in a chronic tendency to form thromboses due to a decreased ability to inhibit coagulation." (PMID 39533629, 2024). "We report a rare case of a 63-year-old female who presented with altered mental status, facial droop, and slurred speech and was found to have an extensive dural venous thrombosis complicated by intracerebral and subarachnoid hemorrhage due to protein S deficiency." (PMID 39268299, 2024). "Thrombosis in BD may be associated with deficiencies in protein C, protein S, and antithrombin III, as well as the presence of antiphospholipid antibodies, factor V Leiden, and the prothrombin 20210A mutations." (PMID 39575088, 2024). "Furthermore, WES identified PROS1 p.Y592* mutation in a 72-year-old man who had protein S deficiency and episodes of large artery atherosclerosis-related infarction and deep vein thrombosis." (PMID 36580209, 2023). "It would be helpful to understand how the ABO blood group interacts with other venous thrombosis risk factors, including genetic (antithrombin, protein C, or protein S deficits) and acquired risk factors (surgery, immobilization, pregnancy, oral contraceptives)." (PMID 36010287, 2022). "C4BPA was also found to be a risk factor for venous thrombosis via an unknown protein S-independent mechanism." (PMID 35935235, 2022).
thrombosis (continued). "Hence, even though protein S deficiency is the rare cause of deep vein thrombosis when recurrent should be considered despite its rare occurrence." (PMID 36705157, 2022). "Whether individuals with PROS1 mutations have thrombosis greatly depends on the interaction between genes and the interaction between genes and the environment." (PMID 34496879, 2021). "Patients with venous thrombosis caused by PROS1 mutations could receive rivaroxaban as the first choice of anticoagulation therapy." (PMID 34967380, 2021). "HIV infection may predispose an individual to arterial and venous thrombosis due to protein C and protein S deficiencies." (PMID 34650658, 2021). "The contraceptives showed a strong association with thrombosis due to their estrogenic component, as estrogen increases the levels of coagulation factors and decreases the levels of anticoagulant proteins such as protein S." (PMID 34940632, 2021). "Indeed, two of the three cases of the stillbirth in the GDM-N group were due to multiple congenital malformation, and the third case was due to placental thrombosis secondary to protein S deficiency." (PMID 33692395, 2021). "Protein S deficiency increased the possibility of venous thrombosis." (PMID 34477132, 2021). "The initiation of HAART might help to reduce protein S deficiency and the risk of thrombosis in HIV-infected individuals." (PMID 34522427, 2021). "In all cases, Protein S deficiency is associated with a higher risk of venous thrombosis." (PMID 32826388, 2020). "Thrombosis of umbilical vessels may be associated with a deficiency in coagulation proteins such as protein S." (PMID 30112236, 2018). "Protein S is a vitamin K-dependent anticoagulant; its deficiency commonly presents with recurrent deep vein thrombosis, thrombophlebitis, or pulmonary embolism, and its prevalence in patients with mesenteric vein thrombosis and in general population are 2.6% and 0.03–0.13% respectively." (PMID 29117862, 2017). "Since other genetic risk factors such as FVL and prothrombin G20120A variants or deficiencies in natural anticoagulants (protein C, protein S and antithrombin) can influence the predisposition to develop venous thrombosis, patients carrying these defects were excluded from our analysis." (PMID 26982741, 2016). "Indeed, inherited Pros1 deficiency (in the Pros1 gene) leads to enhanced deep vein thrombosis and risk for embolism." (PMID 27916840, 2016). "Some reports show patients with an acquired deficiency of antithrombin III, protein C, and protein S. Thrombosis may be serious and life threatening." (PMID 18234096, 2008). "A number of heritable disorders predisposing to thrombosis have been identified, including deficiencies and/or defects of protein C, protein S, antithrombin, factor V and factor II (prothrombin); patients presenting with deep vein thrombosis or pulmonary embolism are often tested for these defects." (PMID 18384680, 2008). "We recently encountered a case of deep vein thrombosis (DVT), highlighting reduced protein S-specific activity despite normal protein S and antigen levels as a potential pathology in patients with protein S Tokushima variant." (PMID 41567132, 2026). "Once activated, APC degrades the regulatory proteins of coagulation factors VIII-a and V-a in the presence of its cofactor, protein S. Deficiencies in protein C or S are strongly associated with the development of deep vein thrombosis (DVT)." (PMID 39941603, 2025). "Among the 11 patients with thrombosis in our study, three exhibited low levels of protein C, protein S, and/or antithrombin III." (PMID 40704143, 2025). "The study found that women with thrombosis had lower protein C and free protein S, and higher D-dimer, prothrombin fragment 1 + 2, and PAP." (PMID 41048432, 2025).
thrombosis (continued). "In contrast, because HIT was induced by heparin administration in the present case, our patient was considered to have thrombosis exacerbated by HIT and also a pathological condition with anti-phospholipid antibody and acquired protein S deficiency." (PMID 39533629, 2024). "Heparin was immediately discontinued because anti-cardiolipin IgG antibody and protein S activity decreased, and because thrombocytopenia and worsening of thrombosis due to HIT were suspected." (PMID 39533629, 2024). "Because only 40% of the protein S that is free is functionally active, only patients with low free protein S levels are prone to venous thrombosis." (PMID 38891849, 2024). "In China, genetic thrombophilia patients mainly suffer from deficiencies in AT III, protein S, and protein C. Multiple mutations in the serpin family C member 1 (SERPINC1) can affect AT III activity, resulting in thrombosis." (PMID 38457560, 2024). "The dual coagulation disorder hereditary protein S deficiency and activated protein C (APC) resistance, which clinically manifests with recurrent venous thrombosis and multifocal ischemic stroke, has only rarely been reported in the same patient." (PMID 36824536, 2023). "For example, mutations in PROS1 lead to protein S deficiency, and MTHFR or Factor V Leiden mutations can lead to hereditary thrombosis." (PMID 36700010, 2022). "However, whole-exome sequencing revealed a thrombotic risk variant (T630I) in the PROS1 gene encoding protein S. This missense variant is often reported in patients with thrombosis or protein S deficiency, and may result in a thrombotic predisposition in some situations, such as nephrotic syndrome." (PMID 32266186, 2020). "Rare mutations in PROC, PROS1 or SERPINC1 as well as common variants in F5, F2, F11 and SERPINC1 have been identified as risk factors for deep vein thrombosis (DVT)." (PMID 26982741, 2016). "The prevalences of APC-R, protein C and protein S in controls were 4%, 0% and 2%; while in patients with venous thrombosis, the corresponding values were 17.9%, 7.7% and 6.6 %, and the differences in all of these were statistically significant." (PMID 21181065, 2010). "Since anticoagulation and acute thrombosis can lower levels of protein C, protein S and antithrombin, it is preferable that testing for these be performed when the patient has recovered from the acute event and is not on anticoagulant therapy." (PMID 18384680, 2008). "Thrombosis occurs in heterozygotes whose levels of functional protein S are in the range of 15–50% of normal." (PMID 16968541, 2006). "In the setting of acute thrombosis or hepatic dysfunction, levels of natural anticoagulants, such as protein C, protein S, and antithrombin III, may be reduced." (PMID 40895862, 2025). "The results showed that three patients had combined PROC or PROS1 mutations, whereas the remaining five did not carry any thrombosis-associated genetic mutations." (PMID 39805289, 2025). "A proteome-wide MR study based on 81 669 VTE cases of multiple ancestries identified 23 proteins associated with VTE, many of which were confirmed in our study, such as those for coagulation FXI, prekallikrein, prothrombin, and protein S with well-defined function in thrombosis." (PMID 38029854, 2024). "It has been reported that congenital protein S deficiency occurs in 1% to 1.75% of cases of deep vein thrombosis, but genetic testing in this case did not identify any congenital anomalies." (PMID 39533629, 2024). "The plasmatic levels of many anticoagulants (protein C, protein S, and antithrombin) may transiently decrease during acute thrombosis." (PMID 35402350, 2022). "Thus, reduced levels of natural anticoagulants including protein C (PROC), protein S (PROS1), and antithrombin (SERPINC1), are not only associated with an increased risk of venous thrombosis, but also with the progression, outcome and prognosis of IS." (PMID 34829993, 2021).
thrombosis (continued). "In the past, we detected a new mutation in PROS1 in a family prone to thrombosis, which had not been previously reported." (PMID 34496879, 2021). "Bovine APC (bAPC) is also highly antithrombotic in arterial thrombosis models in rabbits and rats, but only when co-administered with bovine protein S (bPS), demonstrating the importance of PS as a cofactor to bAPC and the species specificity in the APC-PS interaction." (PMID 18957140, 2008). "Acquired protein S deficiency may be seen in some patients who have developed disseminated intravascular coagulation (DIC), deep vein thrombosis (DVT) or pulmonary embolism (PE)." (PMID 16827935, 2006). "The lifetime probability of developing thrombosis compared to those with no defect was 8.5 times higher for carriers of protein S deficiency, 8.1 for type I antithrombin deficiency, 7.3 for protein C deficiency, and 2.2 for factor V Leiden." (PMID 16968541, 2006). "The establishment of venous thrombosis in post-primary VZV infection is believed to be caused by direct injury to the endothelial cells, inflammation of the blood vessel, the production of autoantibodies against protein S, or an existing condition of increased blood clotting." (PMID 39469279, 2024). "The patient with possible protein S deficiency underwent various guideline-directed medical treatments, yet experienced recurrent VTE episodes, including deep vein thrombosis (DVT) and pulmonary embolism (PE), leading to hospital readmissions." (PMID 38883011, 2024). "In order to further explore whether the risk factors for hereditary thrombosis are involved in the event of APL thrombosis, we detected antithrombin III, protein C, protein S, antiphospholipid antibodies and homocysteine in 7 APL patients with thrombotic events." (PMID 34130694, 2021). "The failure in our series to find decreased levels of protein S in patients with previous thrombosis could reflect the very small number of patients in that category, along with the multiple risk factors that are probably involved in the pathologic hypercoagulability of SLE." (PMID 20637106, 2010). "In the present study assessing 107 SLE patients, free protein S levels were significantly lower only in those patients with ACA, but not in those with LAC and anti-β2 glycoprotein I. Autoantibodies directed against protein S have been associated with thrombosis in patients with APS and SLE." (PMID 20637106, 2010). "A specific focus was to reduce inpatient ordering of protein C, protein S, and antithrombin III levels, which are often rendered inaccurate by acute thrombosis or recent anticoagulation." (PMID 40896077, 2025). "Mutations in PROS1 are a risk factor for thrombosis in Asian populations and repeated spontaneous DVT and pulmonary embolism without obvious reasons are the most common symptoms." (PMID 34496879, 2021). "The family history was negative for thrombosis or protein S deficiency and as aresult an acquired protein S deficiency was considered in this patient, probablysecondary to chronic hepatitis C. On the other hand, cirrhosis may be an underlyingcause of his low protein S levels." (PMID 29349091, 2018). "In a large population-based study, patients with venous thrombosis did not have lower protein S levels as compared with those in the age- and sex-matched healthy controls." (PMID 36078892, 2022). "Venous thrombosis occurs as a result of interaction of genetic and acquired factors including activated protein C resistance (APC-R), fibrinogen levels, antithrombin, protein C, protein S, lupus anticoagulants and anticardiolipin antibodies." (PMID 21181065, 2010). "We could boldly speculate that elevated expression of oncogenic miR-27a-3p not only promotes carcinogenesis but also inhibits the expression of PROS1 in ICC patients, thereby supporting the hypercoagulable state of blood and likelihood of thrombosis in ICC patients." (PMID 31956102, 2020).
thrombosis (continued). "Among five SLE patients with anti-protein S antibodies, four had a history of thrombosis and three patients were positive for ACA; however, their acute levels of free protein S were not different from the patients without anti-protein S antibodies (data not shown)." (PMID 20637106, 2010). "The P values for APC-R, low protein S and protein C, raised fibrinogen and a positive family history were statistically significant while the prevalence of ACL, LA, smoking, dyslipidemia and low AT were higher in the patients but were not significantly related to deep vein thrombosis in this study." (PMID 21181065, 2010).